RNU6-1276P (RNA, U6 small nuclear 1276, pseudogene)
Gene: Small nuclear RNA gene on chromosome 8 (27,773,645 to 27,773,748, forward strand). Ensembl gene ENSG00000202242.
Homologues: Orthologues: chimpanzee U6 (99% identical), macaque U6 (93% identical), mouse Gm24901 (74% identical), dog U6 (67% identical), rat LOC120101966 (65% identical). Paralogues in human: RNU6-1031P (81% identical), RNU6-106P (81% identical), RNU6-1209P (81% identical), RNU6-16P (81% identical), RNU6-29P (81% identical), RNU6-434P (81% identical), RNU6-1099P (80% identical), RNU6-1152P (80% identical), RNU6-1316P (80% identical), RNU6-181P (80% identical), RNU6-211P (80% identical), RNU6-35P (80% identical), and 1287 more.